FADS6 (fatty acid desaturase 6)
Synonyms: FP18279
Gene: Protein-coding gene on chromosome 17 (74,877,295 to 74,893,781, reverse strand). Ensembl gene ENSG00000172782.
Subcellular location: Membrane
Genetic constraint (gnomAD): Loss-of-function variants: 28 observed, 31.13 expected, observed/expected ratio (o/e) 0.9, 90% interval 0.67 to 1.23. The upper end of that interval is the gene's LOEUF score, 1.23, which puts it in group 5 of 6, group 1 being the genes least tolerant of losing a copy. Missense variants: 494 observed, 496.91 expected, observed/expected ratio (o/e) 0.99, 90% interval 0.92 to 1.07. Synonymous variants: 191 observed, 204.3 expected, observed/expected ratio (o/e) 0.93, 90% interval 0.83 to 1.05.
Homologues: Orthologues: chimpanzee FADS6 (96% identical), pig FADS6 (80% identical), dog FADS6 (78% identical), guinea pig FADS6 (76% identical), mouse Fads6 (74% identical), rat Fads6 (74% identical), rabbit FADS6 (51% identical), zebrafish FADS6 (50% identical), Caenorhabditis elegans fat-3 (14% identical), Caenorhabditis elegans fat-4 (14% identical). Paralogues in human: FADS1 (21% identical), FADS3 (21% identical), FADS2 (19% identical).
Diseases named in the same sentence as FADS6 in open-access papers:
FADS6 is named in the same sentence as 6 diseases in open-access papers, as found by Europe PMC text mining. Sharing a sentence is not in itself a finding about the gene and the disease. The quoted sentences say what the papers report.
atopic dermatitis (1 paper, 2024). "In atopic dermatitis, genes mainly related to lipid metabolism (e.g. ACAD8, FADS6, or EBP) as well as disease-specific genes, i.e., Th2 inflammation-related lipid-regulating HSD3B1 were differentially expressed." (PMID 38433843, 2024).
diffuse large B-cell lymphoma (1 paper, 2021). "FADS6 was found to be mutated in Chinese Epstein-Barr virus-positive diffuse large B-cell lymphoma." (PMID 34721037, 2021).
glioma (1 paper, 2023). A benign or malignant brain and spinal cord tumor that arises from glial cells (astrocytes, oligodendrocytes, ependymal cells). "In high-grade gliomas, RYR2, MCHR2, FADS6, HTR2C, CMTM3, APH1A, and PFN1 genes are related to membrane function." (PMID 37239411, 2023).
lymphoma (1 paper, 2018). A malignant (clonal) proliferation of B- lymphocytes or T- lymphocytes which involves the lymph nodes, bone marrow and/or extranodal sites. "LNP1—together with other highly mutated genes, such as FADS6 and TRAK1—was firstly found in this lymphoma, and was verified by Sanger sequencing." (PMID 30106962, 2018).
tumours (1 paper, 2020). "Several genes (including BCR, PCLO, ATXN3, PABPC3, and FADS6) were mutated in two or more PDX tumours." (PMID 33144587, 2020).
FADS6 also shares sentences with these, for which no sentence is quoted: Obesity (1 paper).